TP53TG3F (TP53 target 3 family member F)
Gene: Protein-coding gene on chromosome 16 (33,459,612 to 33,462,249, forward strand). Ensembl gene ENSG00000278848.
Subcellular location: Cytoplasm; Nucleus
Subcellular location (Human Protein Atlas): Centriolar satellite
Gene Ontology:
Cellular component: cytoplasm; nucleus
Homologues: Paralogues in human: TP53TG3 (100% identical), TP53TG3B (100% identical), TP53TG3C (100% identical), TP53TG3D (100% identical), TP53TG3E (100% identical).